RECK (reversion inducing cysteine rich protein with kazal motifs)
Diseases named in the same sentence as RECK in open-access papers (continued):
Sharing a sentence is not in itself a finding about the gene and the disease.
chromophobe carcinoma (1 paper, 2013). "We found increasing RECK levels in different renal neoplasms, from clear cell carcinoma over papillary to chromophobe carcinoma and oncocytoma, in which RECK expression became similar for tumor and normal tissue." (PMID 24131772, 2013).
clear cell carcinoma (1 paper, 2013). "RECK staining intensity discriminated the tumor subtypes increasing gradually from clear cell carcinoma to oncocytoma, but with constantly high levels in the normal tissue." (PMID 24131772, 2013).
cocaine abuse (1 paper, 2007). Disorders related or resulting from use of cocaine. "The observed microarray phenotype in the human hippocampus identified RECK and other region-specific genes that may promote long-lasting structural changes with repeated cocaine abuse." (PMID 18000554, 2007). "Thus, the marked increase in RECK message and protein levels suggests that there may be a build up or enhanced maintenance of a remodeled perivascular space in the hippocampus with chronic cocaine abuse." (PMID 18000554, 2007). "Since MMPs can degrade the entire extracellular matrix, coordinated regulation of RECK, MMP9, CTGF and EphB4 suggests expansion of the extracellular matrix occurs with morphological remodeling of the hippocampus in response to chronic cocaine abuse." (PMID 18000554, 2007). "The results of this analysis suggest a coordinated regulation of hippocampal RECK, MMP9, protocadherins and other proteins of the cytomatrix that have not been demonstrated previously in human postmortem studies of gene expression in chronic cocaine abusers." (PMID 18000554, 2007). "We examined whether the target molecules of RECK, MMP2 and MMP9 were regulated by cocaine abuse." (PMID 18000554, 2007).
coronary atherosclerosis (1 paper, 2024). Atherosclerosis of the coronary vasculature. "The findings suggest that miR-21 downregulates RECK expression by means of inhibiting translation, rather than degradation of target mRNA in patients with coronary atherosclerosis." (PMID 38612895, 2024).
dysplasia (1 paper, 2017). A usually neoplastic transformation of the cell, associated with altered architectural tissue patterns. "The sequential increase in miR-21 expression from hyperplasia through dysplasia to SCC together with hypoxia may act cooperatively to downregulate RECK in the hamster buccal pouch in the present study." (PMID 28515436, 2017).
endometrial cancer (1 paper, 2019). Primary or metastatic malignant neoplasm involving the endometrium (mucous membrane that lines the endometrial cavity). "Genome-wide rare variant analysis using the DiscovEHR cohort identified seven genes and one long non-coding RNA to be associated with endometrial cancer, of which two genes RECK and ATP8A1 were replicated (suggestive threshold P < 0.05)." (PMID 31338326, 2019). "The RECK gene was found to be associated with endometrial cancer and was replicated (p-value < 0.05)." (PMID 31338326, 2019). "Seven genes, including RBM12, NDUFB6, ATP6V1A, RECK, SLC35E1, RFX3 (Bonferroni-corrected P < 0.05) and ATP8A1 (suggestive P < 10−5), and one long non-coding RNA, DLGAP4-AS1 (Bonferroni-corrected P < 0.05), were associated with endometrial cancer." (PMID 31338326, 2019).
fibroids (1 paper, 2016). "Therefore, if there were elevated levels of miR-15b in leiomyoma it may well down regulate the anti-tumor effects of RECK." (PMID 27530410, 2016).
fibrosis (1 paper, 2020). the formation of excess fibrous connective tissue in an organ or tissue in a reparative or reactive process. "Additionally, RECK (reversion-inducing cysteine-rich protein with Kazal motif) a regulator of cardiac fibrosis was found to be significantly upregulated in EMPA treated mice." (PMID 33184414, 2020).
gastric tumor (1 paper, 2024). "They performed a luciferase reporter assay and observed a significant decrease in luciferase activity in the presence of MRE of RECK 3′-UTR cloned in pMSCVpuro-miR-21 in gastric tumor cells compared with the controls." (PMID 38612895, 2024).
gout (1 paper, 2020). A condition characterized by painful swelling of the joints, which is caused by deposition of urate crystals. "Regarding RECK and NPC2, rs186201319 and rs539604468 confounded the relationship between RECK methylation and gout and between NPC2 methylation and gout, respectively." (PMID 32630231, 2020).
head and neck cancer (1 paper, 2024). A primary or metastatic malignant neoplasm affecting the head and neck. "Results indicate that RECK is under-expressed, while miR-21 is overexpressed in head and neck cancer cells compared with the normal tissues." (PMID 38612895, 2024). "An MRE of RECK 3′-UTR and a mutated version were examined by luciferase reporter analyses in head and neck cancer cells." (PMID 38612895, 2024). "The data show that the RECK gene is post-transcriptionally downregulated by miR-21 in head and neck cancer cells." (PMID 38612895, 2024).
hilar cholangiocarcinoma (1 paper, 2009). A cholangiocarcinoma that arises from the junction, or adjacent to the junction, of the right and left hepatic ducts. "The abnormal expression of RECK gene might be one of the molecular mechanisms of hilar cholangiocarcinoma metastasis." (PMID 27933122, 2009).
Huntington disease (1 paper, 2022). Huntington disease (HD) is a rare neurodegenerative disorder of the central nervous system characterized by unwanted choreatic movements, behavioral and psychiatric disturbances and dementia. "In contrast, hGDE2 expression is not impaired in postmortem brain of patients with Huntington’s disease (HD) and RECK release is equivalent to control patient samples." (PMID 35550203, 2022).
invasive carcinoma (1 paper, 2012). A carcinoma that is not confined to the epithelium, and has spread to the surrounding stroma. "Down-regulation of RECK was observed in nearly all invasive carcinoma (92%) and half of the (50%) CIN II/III cases." (PMID 22438955, 2012). "On the other hand, CINII/III and invasive carcinoma samples displayed weak cytoplasmastic RECK staining throughout the lesion." (PMID 22438955, 2012).
ischemia (1 paper, 2020). A hypoperfusion of the BLOOD through an organ or tissue caused by a PATHOLOGIC CONSTRICTION or obstruction of its BLOOD VESSELS, or an absence of BLOOD CIRCULATION. "In addition, no changes in RECK content at the end of ischemia occurred when compared with sham-operated group." (PMID 32403397, 2020). "Although we demonstrated a time-dependent effect of reperfusion injury on the cross-talk mechanisms linking RECK expression to MAPK activity, we cannot rule out the potential impact of the kinetics of the ischemia injury on the activation/expression of the tested signaling cascades." (PMID 32403397, 2020).
keratinization (1 paper, 2019). The process in which the cytoplasm of the outermost cells of the vertebrate epidermis is replaced by keratin. "Moreover, miR-7 and miR-21, two keratinization-associated miRNAs, could influence the modification of the tumor suppressor gene RECK in OC." (PMID 31019584, 2019).
kidney damage (1 paper, 2022). "Empagliflozin reduces systemic and renal arterial stiffness and reverses RECK expression in T2DM female mice, alleviating kidney damage." (PMID 35677689, 2022).
liver disease (1 paper, 2021). "Currently, RECK inducers are being explored in the context of cancer treatment, thus expansion of this research into the area of liver disease could prove fruitful and should be considered." (PMID 34745017, 2021).
malignant glioma (1 paper, 2017). A grade III or grade IV glioma arising from the central nervous system. "We also assessed the effects of DHA on the migrating and invasive capabilities of malignant glioma cells; the results demonstrate that DHA can inhibit the metastasis and invasion ability of malignant glioma cells in a dose- and time-dependent manner mainly via activating RECK." (PMID 28208619, 2017). "Thus, we further investigated whether DHA inhibits the metastasis and invasion of malignant glioma cells by upregulating RECK." (PMID 28208619, 2017). "Western blot analysis showed that DHA could upregulate the protein level of RECK as well as downregulate the marker proteins (N-Cadherin and MMP-2) for migration and invasion ability of cancer cells in malignant glioma cells in a dose-dependent manner." (PMID 28208619, 2017). "However, there is no report focusing on the roles of miR-21 and RECK in the treatment of malignant glioma cells with DHA." (PMID 28208619, 2017).
nephritis (1 paper, 2025). Inflammation of renal tissue. "We discovered that hsa-miR-6516-3p contributes to an increase in the expression of MMP9, which is a factor that exacerbates nephritis, via the suppression of its endogenous inhibitor RECK." (PMID 40045202, 2025).
neuroblastoma (1 paper, 2017). Neuroblastoma (NB) is the most common solid, extracranial childhood tumor. "Further, RECK overexpression can induce ER stress, as demonstrated by the increased level of phosphorylated PERK and eIF-2α, and exert a cytotoxic effect in neuroblastoma cells." (PMID 28134767, 2017). "In contrast, GRP78 overexpression inhibits the RECK-induced expression of phosphorylated PERK and eIF-2α in neuroblastoma cells." (PMID 28134767, 2017). "RECK and GRP78 were shown to colocalize in the cytoplasm and perinuclear area in neuroblastoma cells, indicating that RECK and GRP78 are colocalized in the ER because the glycosylphosphatidylinositol-anchored RECK is transported from the ER to the plasma membrane through the Golgi apparatus." (PMID 28134767, 2017).
neurofibroma (1 paper, 2018). An intraneural or extraneural neoplasm arising from nerve tissues and neural sheaths. "To test this, we performed Western blots and found that RECK was not detectable or expressed at a lower level in human MPNST cells, compared to the benign neurofibroma cell line, HEI193." (PMID 29805750, 2018).
peripheral T-cell lymphoma (1 paper, 2013). "In the present study, RECK expression in peripheral T-cell lymphoma (PTCL; n=82) was examined using immunohistochemistry, and its correlation with clinicopathological factors was analyzed." (PMID 23833658, 2013).
pulmonary sarcoidosis (1 paper, 2016). Sarcoidosis affecting the lung parenchyma. "Further, low mRNA expression of RECK was present in our patients with pulmonary sarcoidosis, COPD and IIPs." (PMID 27575817, 2016).
Renal neoplasm (1 paper, 2013). The presence of a neoplasm of the kidney. "RECK expression was assessed in 395 cases and EMMPRIN expression in 394 cases of renal neoplasms on the TMA." (PMID 24131772, 2013).
sarcoidosis (1 paper, 2016). Sarcoidosis is a multisystemic disorder of unknown cause characterized by the formation of immune granulomas in involved organs. "The subsequent sub-analysis of never smokers showed that AUF1 (p<0.001), TIA (p<0.001), NCL (p<0.01) and RECK (p<0.05) remained to be down-regulated in sarcoidosis compared to healthy controls." (PMID 27575817, 2016). "Among sarcoidosis patients, RECK decreased in parallel with decreasing expression of AUF1 (p = 0.002), NCL (p = 0.02), HuR (p = 0.002), TIA (p<0.001) and TIAR (p = 0.007)." (PMID 27575817, 2016). "mRNA expressions of three RBPs (AUF1, TIA and NCL) and their potential target mRNA encoding RECK in BA cells and additionally protein expression of AUF1 and HuR in PBTLs were down-regulated in our sarcoidosis patients compared to healthy individuals." (PMID 27575817, 2016). "In contrast to PCBP2, the mRNA expression of other RBPs and two inhibitors of MMP-9 (RECK and PTEN) did not correlate with any BA sub-population in our patients with sarcoidosis." (PMID 27575817, 2016).
urothelial carcinoma (1 paper, 2021). A malignant neoplasm derived from the transitional epithelium of the urinary tract (urinary bladder, ureter, urethra, or renal pelvis). "The results demonstrated low expression of PDE5A, RECK, ZEB2, and CYBRD1 in urothelial carcinoma tissue." (PMID 33987019, 2021). "PDE5A, RECK, ZEB2, and CYBRD1 play essential roles by interacting with other miRNAs and genes in urothelial carcinoma networks which are represented by purple circles." (PMID 33987019, 2021).
viral hepatitis (1 paper, 2023). An acute or chronic inflammation of the liver parenchyma caused by viruses. "In addition, the evaluation of the contribution of RECK in viral hepatitis deserves to be studied." (PMID 38139236, 2023).
tumor (133 papers, 2005 to 2026). "RECK is a membrane-anchored protein that regulates MMPs, which are closely associated with the invasion and metastasis of various tumor cells and patient prognosis." (PMID 38686051, 2024). "RECK was significantly associated with patient age, tumor grade, stage, and T classification of STAD." (PMID 37904179, 2023). "The TIMP3 and RECK genes encode for proteins that inhibit matrix metalloproteinase, and have been demonstrated to play a tumor-suppressor role by inhibiting angiogenesis, invasion, and metastasis." (PMID 35625697, 2022). "The integrity of the ECM, which is maintained by RECK, is associated with tumor invasion and metastasis." (PMID 33987019, 2021). "Ectopic expression of RECK reduced cell proliferation and invasive potential and partially abrogated the tumour‐promoting effects caused by miR‐15b overexpression." (PMID 29363862, 2018). "Since its first report, RECK down-regulation has been linked to tumor progression, and it is considered to be an adequate biomarker for a better clinical course for patients diagnosed with various tumors." (PMID 26449734, 2015). "RECK expression was significantly associated with tumor-node-metastasis (TNM) stage (P=0.047), perineural invasion (P=0.019) and histological grade (P=0.006)." (PMID 24765174, 2014). "Recently Jung and co-workers demonstrated that miR-7 is involved in the regulation of the tumor suppressor gene reversion-inducing cysteine-rich protein with kazal motifs (RECK), causing its suppression." (PMID 25909813, 2014). "Tumor microvessel density assayed by CD31 immunostaining showed that RECK knockdown was associated with highly vascularized tumors." (PMID 24376819, 2013). "Numerous studies have suggested that the expression of RECK is associated with tumor metastasis and is useful as an informative prognostic indicator for several neoplastic diseases." (PMID 23833658, 2013). "The membrane-associated MMP inhibitor, RECK (reversion-inducing cysteine-rich protein with Kazal motifs), is able to suppress tumor invasion and metastasis by negatively regulating MMP-2, MMP-9 and MMP-14." (PMID 22260435, 2012). "The RECK gene encodes a membrane-anchored glycoprotein that can negatively regulate matrix metalloproteinases (MMPs) and inhibit tumor invasion, angiogenesis, and metastasis." (PMID 22428065, 2012). "RECK encodes a membrane-associated MMP regulator protein that is able to suppress tumor invasion and metastasis by negatively regulating MMPs involved in carcinogenesis, namely: MMP-2, MMP-9 and MMP-14 (MT1-MMP)." (PMID 19144199, 2009). "This leads to the hypothesis that singular changes within the RECK protein structure itself or promoter polymorphisms could have a significant impact on its activity and ultimately on tumor progression." (PMID 34745017, 2021). "RECK was initially isolated as a transformation suppressor gene against the v-K-ras oncogene; subsequent studies implicated RECK in suppression of tumor growth, angiogenesis, invasion, metastasis and recurrence." (PMID 30287421, 2018). "Some of them corroborate the typical RECK down-modulation as a hallmark of tumor aggressiveness." (PMID 26449734, 2015). "Importantly, detection of normal or elevated RECK levels in tumor samples has been associated with decreased invasiveness and metastatic potential and with improved prognosis as well." (PMID 22438955, 2012). "To investigate whether RECK overexpression can counteract the tumour growth caused by miR‐15b, we cotransfected RECK and miR‐15b overexpression vectors into 22RV1 and PC3 cells and found that RECK overexpression attenuated cell proliferation and invasion promoted by miR‐15b." (PMID 29363862, 2018). "Restored expression of RECK in cancer xenograft models suggests it suppresses tumor growth and/or metastasis." (PMID 41598259, 2026). "Due to its functional versatility during animal development, we only recently began to obtain formal experimental evidence that RECK is a bona fide tumor suppressor." (PMID 41598259, 2026).